EPCAM (epithelial cell adhesion molecule)
Diseases named in the same sentence as EPCAM in open-access papers (continued):
Sharing a sentence is not in itself a finding about the gene and the disease.
prostate carcinoma (continued). "Other CSC-targeting therapies under investigation include monoclonal antibodies against CSC surface markers, for example adecatumumab targeting EpCAM in prostate cancer, and therapies that disrupt pathways enriched in CSCs, such as the Wnt, Notch, and Hedgehog pathways." (PMID 36506091, 2022). "CellSearch®, the only CTC system that has been cleared by the US Food and Drug Administration (FDA) for clinical use in patients with metastatic breast, colorectal and prostate cancer, utilizes anti-EpCAM (epithelial cell adhesion molecule) immunomagnetic beads to capture epithelial CTCs." (PMID 34055642, 2021). "Indeed, in breast and prostate cancers, higher EpCAM expression has been observed in metastatic lesions compared to the primary tumors." (PMID 34209658, 2021). "Epithelial cell adhesion molecule (EpCAM) is overexpressed in 40–60% of prostate cancer cases and might be used as a target for specific delivery of toxins and drugs." (PMID 34298801, 2021). "Additionally, a limited number of CSC markers are currently available but their biological function needs to be fully characterized, such as CSPG4 in multiple cancer types, EGFRvIII and IL13Rα2 in gliomas, and EpCAM in prostate cancer." (PMID 33806296, 2021). "A possible therapeutic target for targeted therapy of prostate cancer might be the epithelial cell adhesion molecule (EpCAM)." (PMID 34298801, 2021). "Based on this observation and assumption, we further extracted the exosomes from the cell culture medium of prostate cancer cells, performed western blot analysis and confirmed their identity using positive exosome markers (Annexin, EpCam, CD54, CD9 and flotillin)." (PMID 33605506, 2021). "In addition, epithelial cell adhesion molecule (EpCAM) serves as another marker in prostate cancer, and also RCC patients." (PMID 33276608, 2020). "In both methods, the major CTC phenotype of the prostate cancer blood samples was CK+EpCAM+." (PMID 33261132, 2020). "EpCAM is reported to have a role in radioresistance and chemoresistance in prostate cancer." (PMID 33490064, 2020). "Thus, several antibody combinations were tried next for detection by flow cytometry of EpCAM in EVs from prostate cancer cells." (PMID 30765839, 2019). "Interestingly, CART cells were developed to target CSC-antigen EpCAM to eliminate prostate cancer, demonstrating that EpCAM-specific CART cells had tremendous therapeutic potential for cancer treatment." (PMID 28290053, 2018). "Enrolling 21 patients, including 13 breast- (61.9%), 5 lung- (23.8%), and one (4.8%) colorectal-, renal-, and prostate-carcinoma patient each, we demonstrate a significant 1.8-fold increase of EpCAM+/K+ CTCs in samples taken 20 minutes post-cement augmentation (P < 0.0001)." (PMID 28775319, 2017). "A study by Armstrong and colleagues showed that more than 80% of CTC in patients with metastatic castration-resistant prostate cancer co-expressed epithelial proteins such as EpCAM and CK with mesenchymal proteins including N-cadherin and the stem cell marker CD133." (PMID 27101285, 2016). "Based on the current study, EpCAM may be additionally used as an imaging target for prostate carcinoma lymph node and bone metastases." (PMID 27690012, 2016). "Based on these results, EpCAM may be a feasible imaging target in prostate carcinoma lymph node and bone metastases." (PMID 27690012, 2016). "Based on previous literature, EpCAM may be used as imaging target for locally recurrent prostate carcinoma." (PMID 27690012, 2016). "This imaging modality should be based on a prostate carcinoma-specific target such as EpCAM." (PMID 27690012, 2016). "Additionally, we found SSX2 is expressed in a CD45−/EpCAM+/CD63+ cell subset in the blood of patients with prostate cancer, a cell subset specifically representing prostate-specific circulating tumor cells." (PMID 27276714, 2016). "EpCAM expression was membranous in prostate carcinoma cells of lymph node and bone metastases." (PMID 27690012, 2016).
prostate carcinoma (continued). "EpCAM has been found expressed in various types of carcinoma, including colon and rectum, gallbladder, liver, esophagus, lung, head and neck, pancreas, ovarian, breast, and prostate carcinoma." (PMID 27690012, 2016). "EpCAM expression in prostate carcinoma metastases has been evaluated in only one study previously." (PMID 27690012, 2016). "Thus, nuclear imaging of EpCAM would be of special interest for prostate carcinoma staging and for monitoring of treatment response." (PMID 27690012, 2016). "The current research evaluates the expression of EpCAM in prostate carcinoma lymph nodes, in matched normal lymph nodes, in prostate carcinoma bone metastases, and in normal bone in order to determine the feasibility of EpCAM as a specific marker for prostate carcinoma staging." (PMID 27690012, 2016). "In addition, our previous studies show that EpCAM+ cells of the human prostate cancer cell line PC3 display higher proliferation rates than EpCAM− or unsorted PC3 cells." (PMID 25636521, 2015). "Nevertheless, a prognostic/diagnostic role of EpCAM in EGFR activated prostate cancer cells should not be ruled out." (PMID 25967040, 2015). "EpCAM is a marker that has been detected on CSCs from prostate cancer." (PMID 25636521, 2015). "Therefore, EpCAM is a novel therapeutic target to sensitize prostate cancer cells to chemo/radiotherapy." (PMID 25019346, 2014). "EpCAM was shown to be up-regulated in prostate carcinomas in a number of studies with IHC staining." (PMID 24289299, 2013). "Although we have used EpCAM based capture and cell surface staining to isolate and identify single prostate cancer CTCs, combinations of capture and staining antibodies can be easily reconfigured for use with the MagSweeper to isolate CTCs from other malignancies or to isolate other cell types." (PMID 23145101, 2012). "In prostate cancer, a subanalysis indicated that EpCAM expression is higher on hormone-refractory tumour tissue than on earlier stages (P=0.015), and that there is a decrease in EpCAM expression with increasing Gleason score (P=0.011)." (PMID 17211480, 2007). "Indeed, EpCAM is highly expressed in lung, colon, intestine, breast, and prostate carcinoma." (PMID 38612911, 2024). "However, given the heterogeneity in EpCAM expression for patients with castration-resistant prostate cancer, the use of EpCAM as a sole biomarker for CTC detection poses some concerns about the detection of PCa cells that express little to no epithelial markers following EMT." (PMID 38607014, 2024). "Indeed, even when captured with an EpCAM retrieval method, CTCs in breast and prostate cancer patients were found to co-express epithelial and mesenchymal markers in progressive disease, bringing up the question of how many EpCAM-negative mesenchymal cells were missed in the analysis." (PMID 35267444, 2022). "However, the expression of EPCAM in prostate cancer is inconsistent." (PMID 35205714, 2022). "However, EpCAM expression in prostate carcinoma metastases has been evaluated in only one study." (PMID 27690012, 2016). "A completed phase I study in hormone-resistant prostate cancer patients has shown that the human antibody was well tolerated at all doses tested, has not reached a maximum tolerated dose at 6 mgkg−1, and showed no signs of pancreatitis, which had been an issue with two high-affinity anti-EpCAM mAbs." (PMID 17211480, 2007). "Epithelial cell adhesion molecule expression results were correlated for the first time with clinico-pathological parameters in colon and lung cancers, while results from a large panel of gastric and prostate cancer samples are being compared to published data." (PMID 16404366, 2006). "Peripheral blood samples were collected from 52 prostate cancer patients, and CETC/CTC were detected using the EpCAM surface marker." (PMID 40004014, 2025).
prostate carcinoma (continued). "The epithelial cell adhesion molecule (EPCAM) is a notable marker and is the only FDA-approved marker for diagnosing breast, colon, and prostate cancers." (PMID 40361369, 2025). "For instance, prostate cancer (PC3) cell has an average size of 15±5μm and ~50,000 surface EpCAM antigens per cell." (PMID 39229148, 2024). "Among these markers, the epithelial cell adhesion molecule (EPCAM) stands out and is the only marker approved by the FDA for the diagnosis of breast, colon, and prostate cancer." (PMID 38612677, 2024). "Other CAR T products targeting Epithelial cell adhesion molecule (EpCAM) and Natural Killer Group 2D (NKG2D) have shown activity in prostate cancer patients as well." (PMID 37842236, 2023). "Antibody-conjugated AgNPs were used to report EpCAM, and antibody-conjugated CuNPs were used to report prostate-specific membrane antigen (PSMA), a biomarker for prostate cancer." (PMID 36770486, 2023). "Currently, three main targets of CAR-T therapy for prostate cancer research are prostate specific membrane antigen (PSMA), prostate stem cell antigen (PSCA), and epithelial cell adhesion molecule (EpCAM)." (PMID 35205714, 2022). "EpCAM, also known as CD236, is a transmembrane glycoprotein expressed in several solid tumours, including prostate cancer." (PMID 35158771, 2022). "To date, the most extensively investigated TAAs preclinically and clinically in the context of prostate cancer are prostate stem cell antigen (PSCA), epithelial cell adhesion molecule (EpCAM) and prostate-specific membrane antigen (PSMA)." (PMID 35158771, 2022). "For example, the CellSearch® system uses nanoparticles labeled with antibodies that target the epithelial cell adhesion molecule (EpCAM) to separate CTC from other cells present in the blood of patients with metastatic colorectal, breast, or prostate cancer." (PMID 34439360, 2021). "In another investigation, CIK cells sensitized by EpCAM and CD44 peptide DCs were effective in vitro against Prostate Cancer Stem like Cell (PCSC)-enriched prostate-spheroids and in vivo against PCSC-enriched prostate-spheroid xenografts." (PMID 33806296, 2021). "We also examined markers for prostate cancer such as AMACR, EPCAM and C-MYC as well as molecular markers CDH1 and PTEN." (PMID 34911933, 2021). "EpCAM positive CTCs that co-express EMT markers were frequently detected in breast and prostate cancer patients." (PMID 34209658, 2021). "For prostate cancer, CARs binding to the prostate-specific membrane antigen (PSMA), the prostate stem cell antigen (PSCA), and EpCAM have been tested in preclinical and phase I clinical trials." (PMID 32326073, 2020). "EpCAM has been evaluated in some preclinical models as an immunotherapeutic target in CART-based and antibody-based immunotherapy for prostate cancer." (PMID 32183880, 2020). "EpCAM is also reported to regulate the AKT/mTOR signaling and, in turn, to be involved in prostate cancer radioresistance." (PMID 33490064, 2020). "Our results demonstrate the potential therapeutic value of CIK-based immunotherapy targeting the EpCAM+ and CD44+ prostate cancer cells or PCSCs." (PMID 32183880, 2020). "Using immunomagnetic selection via EpCAM, HER2, and EGFR, a patient was defined as CTC+ if overexpression of one of the four prostate cancer related genes was detected." (PMID 33014830, 2020). "Biotinylated anti-EpCAM, anti-ITGA3 or anti-CD63 antibodies were applied for capturing EVs from cell culture supernatants of the prostate cancer cell lines LNCaP, DU145 and PC3 and one of the control cell line HEK293." (PMID 31296879, 2019). "Another study of prostate cancer treatment by CART cells, specific for EpCAM, indicated some evidence of anti-tumor efficacy in vitro and in animal models." (PMID 28290053, 2018). "The impact of IL‐6 on CSCs on other prostate cancer cell lines in our panel was measured by FACS, where the fraction of CSCs was measured based on triple‐marker‐positive status (CD44+/CD133+/EpCAM+)." (PMID 29741809, 2018).
prostate carcinoma (continued). "We and others have observed significant vimentin expression within PBMC cell populations; consequently, we used TaqMan assays targeting EpCAM and ARHGAP29 transcripts for specific identification of prostate cancer cells." (PMID 27189161, 2016). "Despite the low expression of EpCAM on PC3 tumor cells, EpCAM-specific PBLs had significant anti-tumor activity against PC3, probably by targeting the CSCs of prostate cancer." (PMID 25636521, 2015). "The current study is the first to present data on the expression of PSMA, EpCAM, VEGF and GRPR in locally recurrent prostate cancer after brachytherapy or external beam radiotherapy." (PMID 24727373, 2014). "Staining for PSMA was seen in 100% (17/17), EpCAM in 82.3% (14/17), VEGF in 82.3% (14/17) and GRPR in 100% (17/17) of prostate cancer specimens." (PMID 24727373, 2014). "The recovery and size of 9 different culture cell lines was determined and compared to the size of EpCAM+CK+CD45−DNA+ CTC from patients with metastatic breast, colorectal and prostate cancer." (PMID 23626725, 2013). "In this study, we assessed EpCAM and CTSL levels with ELISA in prostate cancer tissues and determined the effect of epithelium content on tissue protein quantitation." (PMID 24289299, 2013). "Epithelial cell adhesion molecule (EpCAM)-based enumeration of circulating tumor cells (CTC) has prognostic value in patients with solid tumors, such as advanced breast, colon, and prostate cancer." (PMID 23840710, 2013). "Controls for antibody performance were included with every experiment using two prostate cancer cell lines expressing different levels of PSMA and EpCAM (C4-2:PSMA+/EpCAM+/CD45− and PC3: PSMA−/EpCAM−/CD45−) and the CD45+ leukemia cell line U937." (PMID 22558290, 2012). "Prostate cancer cell lines displayed in vitro medium (PC3) and high (LNCAP) levels of mRNA for EpCAM." (PMID 22590529, 2012). "Additionally, higher levels of EpCAM and PSMA were observed on exosomes from 14 prostate cancer patients compared to healthy individuals, showing potential for cancer diagnosis and treatment monitoring." (PMID 39926198, 2025). "Prostatic Acid Phosphatase (PAP), Epithelial Cell Adhesion Molecule (EpCAM), and Transient Receptor Potential (Trp-p8) are other TAAs that are currently being studied which have the potential to become new CAR-T targets for prostate cancer." (PMID 39996908, 2025). "In the subsequent step, Western Blot analyses confirmed the expression of the target proteins CD44 and EpCAM in the prostate cancer cell line PC3-PSMA and the prostate cancer stem cell-like (PCSC-like) cell line PC3-MM2, whereas the control cell line CHO showed no expression of either antigen." (PMID 39846613, 2025). "EpCAM CAR-T cells have been developed that exhibit effective killing abilities against various tumors, such as AML, gastric, colon/lung/pancreatic, and prostate cancer." (PMID 39996844, 2025). "One cell line, MS-pPC-191ST, showed characteristics of neither epithelial cells, e.g., EpCAM or KRT expression nor prostate cancer cells." (PMID 38704600, 2024). "Additionally, previous research has revealed that EpCAM forms a complex with p85, the regulatory subunit of PI3K, and promotes tumor progression in prostate cancer and nasopharyngeal carcinoma through the regulation of the PI3K/AKT/mTOR pathway." (PMID 38791091, 2024). "The authors concluded that the six genes examined (EpCAM, KRT19, PSA, PSMA, AR and AR-V7) may potentially serve as genetic markers to guide early diagnosis of advanced prostate cancer." (PMID 38607014, 2024). "These include CD3/CD19 and CD3/CD20 BSABs for B-cell lymphoma/leukemia; CD3/BCMA, CD3/FcRH5, and CD3/GPRC5D BSABs for MM; CD3/EpCAM BSABs for peritoneal carcinoma and malignant ascites, CD3/gp100 BSABs for UV; CD3/HER2 BSABs for HER2-positive tumors; and CD3/PSMA BSABs for prostate cancer, etc.." (PMID 38627681, 2024).
prostate carcinoma (continued). "For prostate cancer, CARs have been engineered to target antigens overexpressed on prostate tumors compared to normal tissue, including PSMA, PSCA and epithelial cell adhesion molecule (EpCAM)." (PMID 37762648, 2023). "Target antigens for prostate cancer CAR T cell therapy include prostate-specific antigen, prostate acid phosphatase, prostate-specific membrane antigen (PSMA), prostate stem cell antigen (PSCA), and epithelial cell adhesion molecule (EpCAM)." (PMID 37173782, 2023). "Furthermore, EpCAM CAR-T cells produced significant antitumourigenic results both in vivo and in vitro against both the PC-3 and PC-3M human prostate cancer cells." (PMID 35158771, 2022). "Targets that are frequently pursued by multiple commercial companies include EpCAM in NSCLC, HER2 in advanced breast cancers, prostate-specific membrane antigen (PSMA) in castration-resistant prostate cancers, and carcinoembryonic antigen (CEA) in colorectal cancers." (PMID 34922633, 2021). "Notably, targeting EpCAM is currently recognized as the only FDA-approved marker for detecting CTCs and is recommended by the prostate cancer working group (PCWG3) guidelines." (PMID 34206815, 2021). "Imaging mass cytometry (IMC) revealed that 49% of cytokeratin (CK)-positive LEVs and CTCs were EpCAM-negative, while frequently carrying prostate cancer tumor markers including AR, PSA, and PSMA." (PMID 33801459, 2021). "EpCAM+ CTCs were still identified in the DLA product, despite a previous report that some of these cells might be lost by ISET when examined in prostate cancer patients." (PMID 32272669, 2020). "EpCAM, are found in cancers such as breast and prostate cancers but, are not present in melanoma cells, once the breast and prostate cancer cells are original from epithelia tissue and the melanocytes are derived from neural crest." (PMID 32117980, 2020). "EpCAM has been used in combination with CD44 as a marker to efficiently isolate cancer stem cells in different cancer entities such as colon, breast, pancreas and prostate carcinomas." (PMID 31225512, 2019). "Furthermore, CK18, as an epithelial cell adhesion molecule, has been utilized as a biomarker in FDA approved circulating tumor cell detection technologies for breast and prostate cancers." (PMID 31598152, 2019). "NK-92 cells expressing a first-generation EpCAM-specific CAR or coexpressing IL-15 and a second-generation EpCAM-specific CAR with intracellular signaling domains of CD28 were also developed to treat prostate cancer in mouse models." (PMID 30410941, 2018). "Ag-decorated nanorods conjugated with anti-EpCAM antibodies and chemotherapy agents, selectively bound PC3 prostate cancer cells, and enabled the tracking of the nanorod conjugates via SERS microscopy, while simultaneously delivering chemotherapeutics to the cells." (PMID 29751641, 2018). "For CRPC patients, PSA and PSMA mRNA expression in CTCFAPα indicated that these cells originated from the prostate tumor, which is not unprecedented as EpCAM-/PSMA+ prostate cancer CTCs have also been identified by others." (PMID 29657983, 2017). "Putative EPCAM-positive DTCs from 65 non-metastatic prostate cancer patients were subjected to targeted expression profiling of 17 genes." (PMID 26378808, 2015). "To investigate the therapeutic capabilities of PBLs expressing EpCAM-specific CARs, we used two different tumor models, PC3, the human prostate cancer cell line, which has low expression levels of EpCAM, and PC3M, a highly metastatic clone of PC3 that has high expression levels of EpCAM." (PMID 25636521, 2015).